PKM (pyruvate kinase M1/2)
Description:
Catalyzes the final rate-limiting step of glycolysis by mediating the transfer of a phosphoryl group from phosphoenolpyruvate (PEP) to ADP, generating ATP. The ratio between the highly active tetrameric form and nearly inactive dimeric form determines whether glucose carbons are channeled to biosynthetic processes or used for glycolytic ATP production. The transition between the 2 forms contributes to the control of glycolysis and is important for tumor cell proliferation and survival. [Isoform M2]: Isoform specifically expressed during embryogenesis that has low pyruvate kinase activity by itself and requires allosteric activation by D-fructose 1,6-bisphosphate (FBP) for pyruvate kinase activity. In addition to its pyruvate kinase activity in the cytoplasm, also acts as a regulator of transcription in the nucleus by acting as a protein kinase. Translocates into the nucleus in response to various signals, such as EGF receptor activation, and homodimerizes, leading to its conversion into a protein threonine- and tyrosine-protein kinase. Catalyzes phosphorylation of STAT3 at 'Tyr-705' and histone H3 at 'Thr-11' (H3T11ph), leading to activate transcription. Promotes transcription of VEGFA following translocation to the nucleus along with the NFKB1/p50 and RELA/p65 subunits of the NF-kappa-B transcription factor complex which is triggered by interaction with FOXM1 isoform 5 (FOXM1D) and leads to increased angiogenesis. Its ability to activate transcription plays a role in cancer cells by promoting cell proliferation and promote tumorigenesis. Promotes the expression of the immune checkpoint protein CD274 in BMAL1-deficient macrophages (By similarity). May also act as a translation regulator for a subset of mRNAs, independently of its pyruvate kinase activity: associates with subpools of endoplasmic reticulum-associated ribosomes, binds directly to the mRNAs translated at the endoplasmic reticulum and promotes translation of these endoplasmic reticulum-destined mRNAs (By similarity). Plays a role in caspase independent cell death of tumor cells. [Isoform M1]: Pyruvate kinase isoform expressed in adult tissues, which replaces isoform M2 after birth. In contrast to isoform M2, has high pyruvate kinase activity by itself and does not require allosteric activation by D-fructose 1,6-bisphosphate (FBP) for activity.
Synonyms: CTHBP; THBP1; OIP3; PK3; PKM2; HEL-S-30; TCB; p58
Tractability: Small molecule: a structure with a bound ligand is known; a high-quality ligand is known; it has a high-quality binding pocket; it belongs to a druggable protein family. Antibody: its Gene Ontology location is reachable by antibodies, with high confidence. PROTAC: UniProt records ubiquitination sites on it; ubiquitination databases record sites on it; its protein half-life has been measured; a small molecule that binds it is known.
Target class: Enzyme
Chemical probes: DASA-58, ML082 (high quality), ML083, ML170, ML202, ML285, TEPP-46
Gene: Protein-coding gene on chromosome 15 (72,199,026 to 72,231,819, reverse strand). Ensembl gene ENSG00000067225.
Subcellular location: Cytoplasm (Isoform M2); Nucleus; Cytoplasm (Isoform M1)
Subcellular location (Human Protein Atlas): Cytosol; Principal piece; Vesicles
Pathways (Reactome):
Metabolism: Glycolysis; Pyruvate metabolism; Regulation of pyruvate metabolism
Cell-Cell communication: Negative Regulation of CDH1 Gene Transcription
Immune System: Neutrophil degranulation
Gene Ontology:
Molecular function: cadherin binding; MHC class II protein complex binding; protein binding; protein tyrosine kinase activity; pyruvate kinase activity; RNA binding; mRNA binding; magnesium ion binding; non-membrane spanning protein tyrosine kinase activity; potassium ion binding; protein serine/threonine kinase activity
Biological process: positive regulation of sprouting angiogenesis; programmed cell death; canonical glycolysis; cellular response to insulin stimulus; glycolytic process; positive regulation of cytoplasmic translation; pyruvate biosynthetic process
Cellular component: cytoplasm; cytosol; extracellular exosome; extracellular vesicle; mitochondrion; nucleus; vesicle; extracellular region; ficolin-1-rich granule lumen; nucleoplasm; rough endoplasmic reticulum; secretory granule lumen; cilium
Genetic constraint (gnomAD): Loss-of-function variants: 16 observed, 47.17 expected, observed/expected ratio (o/e) 0.34, 90% interval 0.23 to 0.51. The upper end of that interval is the gene's LOEUF score, 0.51, which puts it in group 2 of 6, group 1 being the genes least tolerant of losing a copy. Missense variants: 481 observed, 704.37 expected, observed/expected ratio (o/e) 0.68, 90% interval 0.63 to 0.74. Synonymous variants: 220 observed, 256.14 expected, observed/expected ratio (o/e) 0.86, 90% interval 0.77 to 0.96.
Homologues: Orthologues: chimpanzee PKM (100% identical), mouse Pkm (98% identical), rat Pkm (98% identical), guinea pig PKM (97% identical), rat Pkml1 (96% identical), tropical clawed frog pkm (89% identical), zebrafish pkma (82% identical), zebrafish pkmb (77% identical), pig PKM (74% identical), Drosophila melanogaster PyK (63% identical), Caenorhabditis elegans pyk-1 (59% identical), Caenorhabditis elegans pyk-2 (55% identical), and 3 more. Paralogues in human: PKLR (71% identical).
Diseases named in the same sentence as PKM in open-access papers:
PKM is named in the same sentence as 352 diseases in open-access papers, as found by Europe PMC text mining. Sharing a sentence is not in itself a finding about the gene and the disease. The quoted sentences say what the papers report.
breast carcinoma (228 papers, 2011 to 2026). "The SNHG3/miR330 axis mainly regulates PKM at the post-transcriptional level to promote glycolysis and proliferation in breast cancer." (PMID 37204526, 2023). "PKM is targeted by miR-330-5p, resulting in an decrease in glycolysis and reduced breast cancer cell proliferation." (PMID 37161350, 2023). "SNHG3 is a molecular sponge for miR-330-5p in breast cancer cells to positively control PKM levels, thus suppressing oxidative phosphorylation (OXPHOS) and enhancing glycolysis to promote cancer proliferation and progression." (PMID 37208722, 2023). "For example, brother of the regulator of imprinted sites can mediate the Warburg effect and promote breast cancer by regulating the methylation of pyruvate kinase M1/2 (PKM) exons." (PMID 36105089, 2022). "The expression profile of SMAR1 and PKM isoforms in breast cancer patients revealed that SMAR1 has an inverse correlation with PKM2 and a positive correlation with PKM1." (PMID 33863392, 2021). "Our study in the breast cancer model highlights that nuclear matrix–binding protein SMAR1 regulates PKM alternative splicing and inhibits the expression of PKM2 and promotes the expression of PKM1." (PMID 33863392, 2021). "Our findings reveal that SMAR1 knockdown promotes the Warburg effect and tumorigenic potential of breast cancer cells by modulating PKM isoform expression indicating an important regulatory role of tumor suppressor protein in cellular homeostasis." (PMID 33863392, 2021). "Further, expression of PKM isoforms upon modulation in SMAR1 expression in breast cancer cell lines was quantified by qRT-PCR and western blot." (PMID 33863392, 2021). "The transcription factor brother of the regulator of imprinted sites (BORIS) regulates the methylation of pyruvate kinase M1/2 (PKM) exons and the alternative splicing of PKM mRNA to mediate the Warburg effect and promote breast cancer." (PMID 35004688, 2021). "Together, these results suggest that the knockdown of CAF-secreted exosomal SNHG3 inhibited breast cancer cell proliferation through increasing miR-330 and decreasing PKM expression." (PMID 31956955, 2020). "In summary, our results demonstrated that knockdown of CAF-secreted exosomal SNHG3 inhibited breast cancer glycosis and growth in vivo by upregulating miR-330 and downregulating PKM." (PMID 31956955, 2020). "CAF-derived exosomes deliver SNHG3 to breast cancer cells, serving as a molecular sponge suppressing miR-330-5p expression; promote breast cancer glycolysis and growth through PKM (miR-330-5p target) modulation." (PMID 32957712, 2020). "Mechanistically, knockdown of exosomal SNHG3 suppressed breast cancer growth and glycolysis in vivo and in vitro through up-regulating miR-330 and decreasing the expression of PKM." (PMID 33077737, 2020). "Recently, we have shown that the PKM splicing switch is regulated epigenetically by DNA methylation-dependent binding of BORIS at exon 10 of PKM gene leading to the inclusion of exon 10 to generate the PKM2 splice isoform in breast cancer." (PMID 31675998, 2019). "In this study, the authors demonstrated that activation of IGF-1/IGF-1R induces HIF-1α/p65 complex formation, which thus binds to the PKM promoter region leading to PKM2 upregulation and PKM2-mediated breast cancer cell growth." (PMID 26739387, 2016). "MiR-122 has been reported to suppress glucose uptake by down-regulating PKM in breast cancer." (PMID 32260506, 2020). "Interestingly, it has been shown that breast cancer (BC) cells inhibit pyruvate kinase (PKM) in pancreatic islet β-cells by secreting miR-122-rich extracellular vesicles, which in turn reduces insulin secretion and leads to dysregulation of glucose homeostasis." (PMID 40881702, 2025). "Another report on breast cancer indicated that the promoters of the rate-limiting glycolytic genes FBP1, PKM and LDHA were specifically methylated in CAFs, where PKM and LDHA expression levels increased, thereby increasing glycolysis in CAFs." (PMID 39408814, 2024).
breast carcinoma (continued). "In breast cancer, the CAF-derived exosome was able to regulate the expression of PKM in cancer cells." (PMID 35910200, 2022). "Immunohistochemistry was performed in breast cancer patient samples to establish the correlation between SMAR1 and PKM isoform expression." (PMID 33863392, 2021). "Moreover, results of in vitro studies have shown that PKM can be targeted by miR-330-5p and is controlled by SNHG3 in breast cancer cells." (PMID 34373744, 2021). "As CCL2, HGF and CCL2/HGF treatment of breast cancer cells led to differences in glucose metabolism, we examined for expression of glycolytic proteins over time, including glucose transporter 1 (GLUT1) and rate limiting enzymes HK2, lactate dehydrogenase (LDHA) and pyruvate kinase M (PKM)." (PMID 40736024, 2025). "On the basis of an inverse correlation between SMAR1 and PKM2 expression as well as a positive correlation between SMAR1 and PKM1 observed in breast cancer, we hypothesized that SMAR1 might play a crucial role in regulating alternative splicing of the PKM gene." (PMID 33863392, 2021). "Moreover, miR-330-5p targeted PKM and regulated by SNHG3 in breast cancer cells." (PMID 33077737, 2020). "Moreover, PKM could be targeted by miR-330-5p and was controlled by SNHG3 in breast cancer cells." (PMID 31956955, 2020).
hepatocellular carcinoma (168 papers, 2013 to 2026). A malignant tumor that arises from hepatocytes. "In hepatocellular carcinoma, SIRT1 and SIRT6 cause de-acetylation at K3, K52, K87, and K350 lysine residues in hnRNPA1, hindering the splicing transition from PKM to PKM2 mRNA." (PMID 38785973, 2024). "We have also found that, in hepatocellular carcinoma cells under hypoxic conditions, Yes1-associated protein (YAP1) and hypoxia-inducible factor 1α (HIF-1α) bind to activate pyruvate kinase M1/2 (PKM2) to promote glycolysis." (PMID 33607990, 2021). "By targeting ADAM metallopeptidase domain 7 (ADAM7) and pyruvate kinase M1/2 (PKM), miR-122 negatively affects in vitro invasion, migration, and survival of hepatocellular carcinoma cells." (PMID 33066509, 2020). "L-alanine is a strong inhibitor of PK-L and hepatoma and has little effect on PK-M while phenylalanine inhibits PKM." (PMID 25621294, 2014). "Among the identified proteins by mass spectrometry, we were interested in pyruvate kinase, muscle (PKM), which is responsible for catalyzing phosphoenolpyruvate into pyruvate in the last step of glycolysis and is highly expressed in bladder cancer and hepatocellular carcinoma." (PMID 32774157, 2020). "Compared to PHCs, the hepatoma cell lines HepG2 and Huh7 exhibited a significant upregulation of glycolysis-related genes, including GLUT1 and PKM." (PMID 40862732, 2025). "ASO targeting PKM splicing increases the PKM1 to PKM2 ratio, thereby redirecting glucose carbons from anabolic processes to the tricarboxylic acid (TCA) cycle in hepatocellular carcinoma and suppressing the liver-tumor formation and growth." (PMID 36140826, 2022). "Our research clearly demonstrated that PKM2 was significantly overexpressed in hepatocellular carcinoma; on the contrary, its isoform PKM1, which is the expression product of PKM gene in normal liver cells, is hardly expressed in HCC." (PMID 34786210, 2021). "In addition, lnc-AROD can enhance hepatocellular carcinoma proliferation by interacting with serine- and arginine-rich splicing factor 3 (SRSF3) to trigger pyruvate kinase M (PKM) switching from PKM1 to PKM2 (23, –, 25)." (PMID 37036350, 2023). "Most evidence shows that miRNAs inhibit glycolysis in tumor cells by targeting the alternative splicing of PKM, and miR-374b affects the splicing of PKM1/PKM2 by changing the expression of hnRNPA1, which makes sorafenib-resistant hepatocellular carcinoma cells sensitive to sorafenib therapy." (PMID 35408903, 2022). "In hepatocellular carcinoma (HCC), METTL3 expression positively correlated with glycolysis genes SLC2A1, HK2, PFKM and PKM." (PMID 33669361, 2021). "Furthermore, in hepatocellular carcinoma (HCC) cells, ERK-mediated nuclear translocation of PKM activates β-catenin in vitro, which induces EMT through the transcription factor, T-cell factor/lymphoid enhancer-binding factor (TCF-LEF)." (PMID 31027222, 2019).
colorectal cancer (157 papers, 2005 to 2025). A primary or metastatic malignant neoplasm that affects the colon or rectum. "METTL1 mediates m7G methylation of PKM mRNA and enhances the expression of its encoded PKM2, while increased PKM2 dimer expression and nuclear translocation activated CD155 expression and induced colorectal cancer immune evasion." (PMID 40443650, 2025). "In recent studies, in order to increase aerobic glycolysis, SNHG6 and hnRNPA1 are lncRNAs that interact to promote the growth of colorectal cancer by regulating alternative splicing of PKM." (PMID 39346921, 2024). "The alternative splicing of the PKM gene is regulated by miR-124, miR-137 and miR-326 in colorectal cancer." (PMID 34298698, 2021). "We previously reported that miR-124 is correlated with prognosis of colorectal cancer due to PKM-dependent regulation of glycolysis." (PMID 24619225, 2014). "To assess the contribution of these enzymes to the formation of phosphoglycolate, we transduced the HCT116 colorectal cancer cell line with lentiviral constructs driving the expression of shRNAs specific for PKM (coding for pyruvate kinases M1 and M2) or GLYCTK (coding for glycerate kinase)." (PMID 30670572, 2019). "Other studies also related Sam68 to PKM alternative splicing and PKM2 overexpression in colorectal cancer." (PMID 37792222, 2024). "In colorectal cancer, miR-124, miR137, and miR-340 regulate the switch of PKM gene expression from PKM2 to PKM1." (PMID 36013278, 2022). "The hnRNP family was reported to play a critical role in the specific splicing of PKM mRNA, which is able to increase the ratio of PKM2:PKM1 and enhance aerobic glycolysis in colorectal cancer cells." (PMID 34786210, 2021). "Moreover, lncRNA SNHG6 binds to hnRNPA1 and subsequently facilitates hnRNPA1-mediated splicing of PKM, resulting in an increased PKM2/PKM1 ratio, aerobic glycolysis and carcinogenic progression in colorectal cancer." (PMID 40612109, 2025). "Here, we found that kaempferol could inhibit the expression of PKM2, the key enzyme of glycolysis, and the three splicing factors of the PKM gene, PTBP1, hnRNPA1 and hnRNPA2, thus reversing the resistance of colorectal cancer cells to 5-Fu." (PMID 35408903, 2022).
lung carcinoma (118 papers, 2011 to 2026). "Another study shows that the overexpression of miR-133b in the lung cancer cell line, A549, re-sensitized the radioresistant A549 cells by targeting pyruvate kinase M1/2 (PKM, also known as PKM2) to regulate glycolysis." (PMID 36428980, 2022). "We also found the alternative splicing pattern of the PKM gene, a kinase of pyruvate and its splicing pattern highly expressed in lung cancer cells, which is regulated by IGF2BP3." (PMID 32984260, 2020). "It has been reported that knock-down of either PKM isoforms in lung carcinoma cell lines H1299 and A549 resulted in different phenotypes, due to deficiency in AMP-activated protein kinase signaling in A549 cells." (PMID 33292198, 2020). "Of note, a recent study showed IGF2BP3 may regulate alternative splicing of PKM in lung cancer." (PMID 34321607, 2022).